TUSC8 (tumor suppressor candidate 8)
Synonyms: XLOC_010588; formerly LINC01071
Gene: Long non-coding RNA gene on chromosome 13 (44,397,630 to 44,414,920, reverse strand). Ensembl gene ENSG00000237361.
Diseases named in the same sentence as TUSC8 in open-access papers:
TUSC8 is named in the same sentence as 9 diseases in open-access papers, as found by Europe PMC text mining. Sharing a sentence is not in itself a finding about the gene and the disease. The quoted sentences say what the papers report.
cervical cancer (4 papers, 2015 to 2024). A primary or metastatic malignant neoplasm involving the cervix. "As lncRNA TUSC8 was relatively rare studied in cancer development process, it had been reported to inhibit metastasis of cervical cancer cells." (PMID 32039833, 2020). "Previous studies have shown that over-expression of TUSC8 could inhibit the invasion and migration of cervical cancer cells by up-regulating PTEN via miR-641." (PMID 32039833, 2020).
breast carcinoma (3 papers, 2020 to 2021). "For the clinical relevance and diagnostic value in breast cancer patients, the ROC analyses indicated that the combination usage of TUSC8 and MYLIP might become novel promising biomarkers and targets for breast cancer diagnosis and treatment." (PMID 32039833, 2020). "And the ROC analysis suggested that TUSC8 might serve as a promising diagnostic biomarker for breast cancer." (PMID 32039833, 2020). "However, the biological functions and underlying molecular mechanisms of TUSC8 with respect to breast cancer remain largely unclear." (PMID 32039833, 2020). "We demonstrated that TUSC8 inhibited tumor growth and metastasis of breast cancer cells through sponging miR-190b-5p, leading to the down-regulation of MYLIP." (PMID 32039833, 2020). "In order to further evaluate the diagnostic values of TUSC8 and MYLIP in breast cancer, we used the receiver operating characteristic curve (ROC) analyses to assess the potential use of these two biomarkers for differentiation of breast cancer patients." (PMID 32039833, 2020). "To identify the expression pattern of TUSC8 in breast cancer progression, we observed the significant down-regulation of TUSC8 expression in breast cancer samples (n=1104) compared with adjacent normal breast tissues (n=113) in TCGA database (p < 0.01)." (PMID 32039833, 2020). "Taken together, these results suggested that TUSC8 inhibited breast cancer growth and metastasis via miR-190b-5p/MYLIP axis, providing us new insights into developing potential therapeutic targets for breast cancer patients." (PMID 32039833, 2020). "In this study, we focused on investigating the functional roles of TUSC8 in breast cancer development." (PMID 32039833, 2020). "To explore the biological functions of TUSC8 in breast cancer development, we established the stable TUSC8 over-expression and knock-down cell lines." (PMID 32039833, 2020). "Here, we found that TUSC8 was significantly down-regulated in breast cancer tissues and its high expression predicted better prognosis of breast cancer patients." (PMID 32039833, 2020). "The correlation between TUSC8 expression and clinicopathological characteristics of breast cancer patients." (PMID 32039833, 2020). "Functionally, knock-down of TUSC8 drastically promoted the proliferation, migration and invasion of breast cancer cells in vitro and facilitated tumorigenicity and metastasis in vivo." (PMID 32039833, 2020). "To investigate the underlying mechanisms of TUSC8 in breast cancer, we first checked the subcellular location of TUSC8 in breast cancer cells by using IncLocator prediction database and RT-PCR assays for cytoplasm and nucleus RNA expression." (PMID 32039833, 2020). "In the following step, we verified TUSC8 down-regulation in an expanded breast cancer sample cohort and conducted the clinicopathological correlation analysis using median cut-off method." (PMID 32039833, 2020). "The results revealed that low expression of TUSC8 was significantly associated with aggressive tumor behavior in large tumor size (p=0.0009), tumor encapsulation (p=0.005), venous invasion (p=0.002) and advanced TNM staging (p=0.002) of breast cancer patients." (PMID 32039833, 2020). "Clinically, the receiver operating characteristic curve (ROC) analyses revealed that the combination usage of TUSC8 and MYLIP might become novel promising diagnostic biomarkers for breast cancer." (PMID 32039833, 2020). "In addition, TUSC8 significantly suppressed the proliferation, invasion and metastasis of breast cancer cells in vitro and repressed tumorigenicity in vivo." (PMID 32039833, 2020). "In this study, we discovered the functional roles of a novel lncRNA TUSC8 in breast tumorigenesis for the first time and demonstrated that TUSC8 was significantly down-regulated in breast cancer tissues and its high expression predicted better prognosis of breast cancer patients." (PMID 32039833, 2020).
breast carcinoma (continued). "For the TUSC8 expression levels in breast cancer cell lines, the data indicated that TUSC8 expressions were significantly down-regulated in multiple breast cancer cell lines compared with normal breast cancer cell line MCF-10A by RT-PCR assay (p < 0.05, p < 0.01 respectively)." (PMID 32039833, 2020). "The biological functions and underlying molecular mechanisms of TUSC8 with respect to breast cancer remain largely unclear, suggesting that TUSC8 might be a novel research field for breast tumorigenesis." (PMID 32039833, 2020). "Moreover, the clinicopathological correlation analysis revealed that low expression of TUSC8 was significantly associated with aggressive tumor behavior in large tumor size, tumor encapsulation, venous invasion and advanced TNM staging of breast cancer patients." (PMID 32039833, 2020). "Moreover, for the overall survival and prognosis value of TUSC8 in breast cancer patients, the curve demonstrated that the high expression of TUSC8 showed better overall survival of breast cancer patients compared with low expression group in TCGA database and GSE dataset." (PMID 32039833, 2020). "We then explored whether TUSC8 regulates breast cancer metastasis via miR-190b-5p-MYLIP axis." (PMID 32039833, 2020). "Thus, we reported that a novel regulatory pathway composed of TUSC8/miR-190b-5p/ MYLIP was involved in the progression of breast cancer, providing us novel insights and avenues for searching potential biomarkers and therapeutic targets for breast cancer diagnosis and treatment." (PMID 32039833, 2020). "Using RT-PCR assay in tumorous and adjacent normal breast tissues in 32 cases of breast cancer patients, we identified that TUSC8 and MYLIP were significantly down-regulated in breast cancer (p < 0.001)." (PMID 32039833, 2020). "The results showed that TUSC8 over-expression reduced the cell invasive capacities in breast cancer cell lines SK-BR-3 and MDA-MB-435 (p < 0.05), whereas TUSC8 inhibition enhanced the cell invasive capacities in breast cancer cell lines MCF-7 and HCC1937 (p < 0.05)." (PMID 32039833, 2020). "Therefore, we constructed the ceRNA network of TUSC8, miR-190b-5p and MYLIP in breast cancer development." (PMID 32039833, 2020). "Finally, we found that miR-190b-5p was a more suitable candidate which showed the opposite expression pattern with both TUSC8 and MYLIP in breast cancer cells." (PMID 32039833, 2020). "The western blot and the band intensity analysis hinted that over-expression of TUSC8 down-regulated the expression of mesenchymal related markers (ZEB1, TWIST, SNAI1 and Vimentin) in breast cancer cell lines SK-BR-3 and MDA-MB-435 (p < 0.05, p < 0.01 respectively)." (PMID 32039833, 2020). "Conversely, knock-down of TUSC8 up-regulated the expression of mesenchymal related markers (ZEB1, TWIST, SNAI1 and Vimentin), and down-regulated the expression of epithelial related marker (E-cadherin) in breast cancer cell lines MCF-7 and HCC1937 (p < 0.05, p < 0.01 respectively)." (PMID 32039833, 2020). "Therefore, in this study we investigated whether EMT is a key factor for TUSC8-mediated cancer metastasis and checked various EMT related markers expression in breast cancer cell models." (PMID 32039833, 2020). "Furthermore, the lncRNA tumor suppressor candidate 8 (TUSC8) can inhibit the evolution of papillary thyroid carcinoma via the miR-190b myosin regulatory light chain interacting protein (MYLIP) axis, which in turn can inhibit breast cancer growth and metastasis." (PMID 35174066, 2021).
gastric cancer (2 papers, 2020). A primary or metastatic malignant neoplasm involving the stomach. "For the remaining three lncRNAs – LINC01089, TUSC8 and CAHM — the LncRNADisease2 database used computational methods and predicted they are associated with gastric cancer." (PMID 32024523, 2020). "Furthermore, TUSC8 (LINC01071) showed consistent down-regulation in gastric cancer (GC) compared with adjacent non-tumor tissues and was significantly correlated with the age and gender of the GC patients, respectively." (PMID 32039833, 2020).
esophageal cancer (1 paper, 2021). A primary or metastatic malignant neoplasm involving the esophagus. "Identically, decreased TUSC8 expression was detected in esophageal cancer cell lines compared with control cells." (PMID 34659529, 2021). "After intervening TUSC8 expression in esophageal cancer cells, the proliferative and migratory abilities were examined in OE19 and TE-1 cells through a series of function experiments." (PMID 34659529, 2021). "TUSC8 inhibits the proliferative and migratory abilities in esophageal cancer cells in vitro by negatively regulating VEGFA." (PMID 34659529, 2021). "Low TUSC8 expression predicted poor prognosis in patients with esophageal cancer." (PMID 34659529, 2021). "Overexpression of VEGFA could reverse the regulatory effects of TUSC8 on esophageal cancer cell proliferation and migration." (PMID 34659529, 2021). "Finally, the co-regulation of TUSC8 and VEGFA on esophageal cancer cell functions was evaluated." (PMID 34659529, 2021).
non-small cell lung carcinoma (1 paper, 2023). A group of at least three distinct histological types of lung cancer, including non-small cell squamous cell carcinoma, adenocarcinoma, and large cell carcinoma. "The TUSC8 gene encodes a non-coding RNA (ncRNA), TUSC8, and this ncRNA reportedly enhances the cisplatin sensitivity of non-small-cell lung cancer cells by regulating vascular endothelial growth factor A (VEGFA), although the involvement of this ncRNA in opioid sensitivity remains unknown." (PMID 37176129, 2023).
tumor (5 papers, 2020 to 2025). "Another lncRNA, TUSC8, demonstrated tumour-suppressive roles in cervical cancer where it focuses on the inhibition of invasion and migration through the miR-641/PTEN axis, similar to PTENP1, but with a specific miRNA target." (PMID 40242248, 2025). "TUSC8 (tumor suppressor candidate 8) is an example of downregulated in NSCLC lncRNA with tumor suppressive function." (PMID 37686426, 2023). "By upregulating PTEN, TUSC8 curtails pathways essential for cancer cell invasiveness, supporting a role that complements both MEG3 and PTENP1 in modulating the tumor microenvironment." (PMID 40242248, 2025). "In addition, most lncRNAs are up-regulated to sponge microRNAs and promote cancer development and progression, while, some of them are down-regulated and act as tumor suppressors; these include lncRNAs STXBP5-AS1, TUSC8, PTENP1, and CASC2." (PMID 34703793, 2021).
cancer (4 papers, 2020 to 2021). A tumor composed of atypical neoplastic, often pleomorphic cells that invade other tissues. "The lncRNA tumor suppressor candidate 8 (TUSC8) plays a critical role in the development of several cancers." (PMID 32039833, 2020). "Also, the inhibition of MYLIP downregulation by TUSC8 resulted in suppressed metastasis showing the important role of MYLIP in cancer." (PMID 32899424, 2020).
TUSC8 also shares sentences with these, for which no sentence is quoted: cervical tumor (1 paper); papillary thyroid carcinoma (1).